MUC4 (mucin 4, cell surface associated)
Diseases named in the same sentence as MUC4 in open-access papers (continued):
Sharing a sentence is not in itself a finding about the gene and the disease.
infection (28 papers, 2007 to 2024). The state of being infected such as from the introduction of a foreign agent such as serum, vaccine, antigenic substance or organism. "In pigs, a decrease of MUC4 gene expression has been associated with ST infection, and genetic variants in this gene have been associated with the increase of gene expression relative to immune function and gut homoeostasis." (PMID 35976909, 2022). "In this study, we established a highly reproducible PWD infection model by examining differences in adhesion of ETEC to the intestinal tissue as well as the association between MUC4 polymorphisms and sensitivity to PWD." (PMID 32784676, 2020). "Susceptibility to this infection is inherited as a Mendelian dominant trait, and we characterised the porcine MUC4 gene and the four neighbouring genes for exonic and intronic mutations." (PMID 21718470, 2011). "As MUC4 is an obvious prime candidate gene for susceptibility to infection by ETEC F4ab/ac, we identified the whole 5' and 3' untranslated regions using Rapid Amplification of cDNA Ends (RACE)." (PMID 21718470, 2011). "Meanwhile, gene expression analysis revealed that in the ΔsaaS group, Muc1 (encoding Mucin-1) had higher expression at 6 hpi; Muc2 (encoding Mucin-2) had higher expression throughout infection; while Muc4 (encoding Mucin-4) had higher expression at 72 hpi and 120 hpi." (PMID 37158502, 2023). "MUC1 and MUC4 are closely related mucins; MUC4 had the strongest inhibition among these SHREKs in our infection assay." (PMID 34064525, 2021). "BALB/c mice were infected with HMPV, and the expression of Muc1, Muc2, Muc4, Muc5ac, Muc5b, Muc15, Muc16, Muc19, and Muc20 were analyzed at 12, 24 and 48 h after infection." (PMID 32899224, 2020). "Experimental infection revealed that PWD can be induced in all MUC4 genotypes after infection with 1010 CFU/pig of highly adherent ETEC, although there were variable sensitivities between the genotypes." (PMID 32784676, 2020). "Although only 56% of partially susceptible pigs in the infection treatment groups developed diarrhea, the results were influenced by the success of the different infection methods and the pigs MUC4/− status." (PMID 31545364, 2019). "MUC4 protein was expressed in gastric mucosa after 3 months of H. felis infection; furthermore, the area of MUC4-positive mucosa expanded as infection continued." (PMID 29212456, 2017). "We have previously found that the expression of porcine MUC13 and MUC4 was down-regulated in IPEC-J2 cells post infection with the same F4ac ETEC strain, and the expression of ITGB5 was not significantly decreased." (PMID 23922972, 2013). "On the fourth day after infection, the n-3 PUFAs enriched diet has a high suppressive effect on the level expression of Muc4 (p < 0.005)." (PMID 17550583, 2007). "Additionally, we identified 10 genomic regions associated with breakthrough infection (SLC6A20, ST6GAL1, MUC16, FUT6, MXI1, MUC4, HMGN2P18-KRTCAP2, NFKBIZ and APOC1), and one with breakthrough severity (APOE)." (PMID 39384777, 2024). "For example, identified loci near MUC4 and MUC16 were supported by genetic variants that increased mucin expression in cilial lung tissue that might be protective for infection." (PMID 36554876, 2022). "Finally, it has been established that MUC4 (mucin 4, cell surface associated) and more generally MUC genes have an important role in preventing pathogens infections." (PMID 35976909, 2022). "We performed similar experiments on the inhibition of Ha-CoV-2 infection by SHREKs, and found that in addition to PSGL-1, CD164, TIM-1, MUC1, and MUC4 also inhibited the infection of Ha-CoV-2 virus; The MUC4 vector had the strongest inhibition among these SHREKs." (PMID 34064525, 2021). "Therefore, with this development of a highly accurate PWD infection model, we recommend the use of pigs with the MUC4 gene (RS or SS) infected with 1010 CFU/pig with highly adherent ETEC." (PMID 32784676, 2020).
infection (continued). "This could explain the lower infection rate and indicate that DNA sequencing should be undertaken to identify MUC4+/− propensity." (PMID 31545364, 2019). "Through the integrated analysis of miRNA-mRNA expression profiles, it was found that the expression of FOXN4, MUC4, KLK1 and CD163 were up-regulated under the action of miR-106b-3p after infection." (PMID 38178220, 2024). "In contrast, G5P infection decreased expression of transmembrane mucin genes significantly (MUC12, MUC16 and MUC21) or numerically (MUC1, MUC4, MUC13 and MUC20)." (PMID 37848925, 2023). "Regarding mucin expression, we showed that infection by both S and R Mabs inhibited MUC5B and MUC4 expression." (PMID 37619220, 2023). "The protective function of mucins against 229E and PIV3 infection was further confirmed for MUC1- and MUC4-overexpressing cells." (PMID 35879412, 2022). "To determine the impact of membrane-anchored mucins on infection of diverse SARS-CoV-2 clinical isolates, we infected our MUC1 and MUC4 GOF Calu-3 lines with alpha (B.1.1.7), beta (B.1.351), gamma (P.1), epsilon (B.1.429) and WA/1 variants." (PMID 35879412, 2022). "Compared to uninfected cells, HMPV infection induced a significant fold-increase expression of MUC1 (8.3 ± 2), MUC2 (43.4 ± 13), MUC4 (54 ± 12), MUC5ac (23.3 ± 11.5) and MUC19 (77 ± 35), while no significant induction of MUC15, MUC16 and MUC20 was observed." (PMID 32899224, 2020). "Infection of isolates BE/ANT-B13/17 and BE/ANT-B20/17 resulted in the highest increase of MUC4 mRNA expression among the RSV-B isolates." (PMID 31698728, 2019). "Infection of BE/ANT-A1/16 and BE/ANT-A11/17 resulted in the highest relative increases of MUC4 mRNA among all of the RSV-A clinical isolates, whereas BE/ANT-A7/17 and BE/ANT-A12/17 resulted in the lowest increase." (PMID 31698728, 2019). "Secondly, we assessed the relative effects of ITGB5 and MUC13 on mRNA expression of the two mucin genes (MUC4 and MUC20) in response to 3 h infection with ETEC strain 200 (MOI = 8∶1) at 44 h after siRNAs transfection." (PMID 23922972, 2013). "Overexpression of TM mucins MUC1, MUC4 or MUC21 reduced infection by SARS-CoV-2 compared to cells with a non-targeting guide (NTG)." (PMID 37561789, 2023). "On the examination of infection in mice lacking MUC4, it was found that MUC4 does not regulate SARS‐CoV titer." (PMID 33373502, 2021). "Female but not male Muc4 knockout mice display increased disease severity after infection with SARS-CoV, suggesting that the Muc4 transmembrane mucin plays an important protective role in female mice during coronavirus pathogenesis." (PMID 33184103, 2020). "It is clear that high-precision and reproducible experimental infection is possible regardless of pig breeds by controlling factors on the pig-end (MUC4 genotype) and factors on the bacterial-end (adhesion ability)." (PMID 32784676, 2020). "However, further research is needed to increase the infection rate and ETEC shedding in MUC4+ pigs by determining other factors involved and/or altering the delivery method of the ETEC-F4 to ensure accurate dosage." (PMID 31346463, 2019). "Therefore, it is important to select and allocate experimental pigs to the dietary treatments based on presence/absence of the MUC4 gene G/C profile to eliminate this confounding factor in nutrition studies using the ETEC-F4 infection model." (PMID 31346463, 2019). "Similarly to the mucus changes during different time points of infection in WT animals, Muc1, Muc2, Muc4 or Muc6 mRNA levels did not explain the differences in mucus thickness between IFN-γ−/- and WT mice." (PMID 30665337, 2019).
adenocarcinoma (12 papers, 2004 to 2023). A common cancer characterized by the presence of malignant glandular cells. "More specifically, Lactobacillus was found to be significantly more abundant in adenocarcinomas with high MUC4 and MUC13 expression." (PMID 37085819, 2023). "Specifically, hepatocyte nuclear factor (HNF) 1α and HNFα transcription factors potentiate the bile acid upregulation of MUC4 and, consequently, the expression of MUC4 increases in oesophageal metaplasia and adenocarcinoma." (PMID 37958425, 2023). "Increased mucin expression, especially MUC1 and MUC4, occurs in many adenocarcinomas." (PMID 28177878, 2017). "Among the 197 adenocarcinoma lesions, MUC4/1G8 was expressed in 95 lesions (48%)." (PMID 23152882, 2012). "Among the 197 adenocarcinoma lesions, MUC4/8G7 was expressed in 83 lesions (42%)." (PMID 23152882, 2012). "The results of this analysis were confirmed by Cox regression analysis adjusting for possible confounders, demonstrating that MUC1 and/or MUC4 expression was indeed an independent prognostic factor among patients with pancreatobiliary differentiated adenocarcinomas." (PMID 19236510, 2009). "Combining MUC1 and/or MUC4 expression at these levels (MUC1 > 40% and/or MUC4 > 0%, versus MUC1 < 40% and MUC4 = 0%) indicated a clear survival disadvantage for patients with pancreatobiliary differentiated adenocarcinomas (P = 0.009)." (PMID 19236510, 2009). "Two cases of CEA-negative adenocarcinoma, one of which was negative for Claudin 4 too, showed MUC4 expression (immunohistochemical score of 2+ or 3+)." (PMID 29317712, 2018). "Although the number of tissue sections were limited for adenocarcinoma (N = 8), no or focal MUC4 reactivity was observed (mean H-score 0.4±0.22)." (PMID 24671186, 2014). "There was one adenocarcinoma case which was negative for both CEA and Claudin-4 but positive MUC4 expression." (PMID 29317712, 2018). "Moreover, 3 cases of Claudin 4-negative adenocarcinoma, two of which were negative for CEA too, showed MUC4 expression (immunohistochemical score of 1+ or 2+)." (PMID 29317712, 2018). "Additionally during the study, low expression of MUC4 in comparison to non-neoplastic bladder urothelium was observed in SCC and adenocarcinoma." (PMID 24671186, 2014).
head and neck tumours (1 paper, 2016). "Similar to our results, whole exome sequencing study of HPV negative versus HPV positive head and neck tumours identified MUC4, 12 and 16 as mutated." (PMID 27829003, 2016).
infectious disease (1 paper, 2025). A disorder directly resulting from the presence and activity of a microbial, viral, or parasitic agent in humans. "DNA tests can currently detect susceptibility to several infectious diseases: polymorphism in the FUT1 gene and the mucin 4 (MUC4) gene determine the susceptibility to Escherichia coli, and the natural resistance-associated macrophage protein 1 (NRAMP1) gene is involved in resistance to Salmonella." (PMID 41465565, 2025).
inflammation (1 paper, 2017). Aberrant reaction of the microcirculation characterized by movement of fluid and leukocytes from the blood into extravascular tissues. "In the present study, we demonstrated that the transcript levels for muc1, muc2, muc3, muc4, muc5b and muc13 in lung tissue were unaltered, whereas muc5ac transcript expression was significantly increased during allergen-induced airway inflammation in mice." (PMID 28205598, 2017).
neurological disorder (1 paper, 2017). "MUC4 encodes a mucin that is expressed in epithelial cells and does not represent a convincing candidate for a neurological disorder." (PMID 29057844, 2017).
reproductive diseases (1 paper, 2025). "We previously reported a potential association between mucin 4 (MUC4)—a member of the same mucin family as MUC2—and reproductive diseases such as RPL, demonstrated by biomarkers." (PMID 40724834, 2025).
MUC4 also shares sentences with these, for which no sentence is quoted: Infertility (5 papers); hepatocellular carcinoma (3); hyperplastic polyp (3); lung disease (3); osteosarcoma (3); anaplastic astrocytoma (2); brain cancer (2); cystic fibrosis (2); endocervical adenocarcinoma (2); escherichia coli infection (2); Hypertension (2); mucositis (2); renal cell carcinoma (2); thymoma (2); uterine corpus endometrial carcinoma (2); acinic cell carcinoma (1); adenocarcinoma of the bladder (1); Airway obstruction (1); angiomyxoma (1); bacterial infection (1); benign meningioma (1); bladder urothelial carcinoma (1); blepharitis (1); bronchiectasis (1); carcinoma in situ (1); cervical dysplasia (1); cholelithiasis (1); chronic obstructive pulmonary disease (1); chronic otitis media (1); chronic periodontitis (1).
A further 47 diseases each share a sentence with MUC4 in 1 paper.